LAG3 (lymphocyte activating 3)
Diseases named in the same sentence as LAG3 in open-access papers (continued):
Sharing a sentence is not in itself a finding about the gene and the disease.
tumor (continued). "Our results showed that TCR clonality was associated with tumor malignant behavior, which might be associated with exhausted CD8 + T cells expressing high levels of T cell immunoglobulin mucin receptor 3 (TIM-3) and lymphocyte activation gene 3 (LAG-3)." (PMID 38280010, 2024). "The anti-TIGIT antibody, anti-LAG-3 antibody, and anti-PD-1 antibody treatment groups could only slightly inhibit tumor growth, with mean tumor volumes of 446.66 ± 25.72 mm3 (TGI = 24.38%), 357.18 ± 63.73 mm3 (TGI = 44.40%), 374.64 ± 66.09 mm3 (TGI = 40.23%) respectively." (PMID 38724599, 2024). "Future exploration of tumor immunobiology and advances in mAb (glyco)engineering will certainly produce novel ICIs that hit other immune checkpoints, such as lymphocyte activation gene 3 (LAG-3 or CD223), expressed on T-cells, Treg, B-cells, NK, and myeloid cells." (PMID 39518937, 2024). "Comprehensive tumour profiling included whole exome sequencing for tumour mutational burden (TMB) and ultraviolet(UV) signatures, and immunohistochemistry for immune-cell infiltration (CD4/CD3/CD8/CD103/CD20) and immune-checkpoint expression (PD-L1/LAG3/TIGIT)." (PMID 38672534, 2024). "Furthermore, elevated expression of LAG3 was observed in tumor‐infiltrating immune cells." (PMID 39565059, 2024). "However, the increased anti-tumour immune response with combined anti-LAG-3 and anti-PD-1 therapies comes with the cost of higher immune-related adverse events (irAEs), with 21.1% of patients on combination therapy experiencing grade 3 or 4 events compared to 11.1% with anti-PD-1 monotherapy." (PMID 39337605, 2024). "Interestingly, we noted a significant downregulation of the expression of multiple coinhibitory molecules associated with CAR-T cell exhaustion, including LAG-3, PD-1, and TIM-3, in ITK-KO CD19-CAR-T cells compared with nt-KO CD19-CAR-T cells 48 hours after coculture with tumor cells." (PMID 39589809, 2024). "However, the role of LAG-3 in the tumor microenvironment is not limited to T cells." (PMID 39252941, 2024). "Therefore, regardless of the overall abundance of immune cells, the presence of specific subsets (such as stem-like TCF1+ or PD-1+ TIM-3- LAG-3- CD8+ T cell subsets) may be crucial for eliciting effective anti-tumor responses 57-58." (PMID 38993563, 2024). "To determine if LAG-3+tumor infiltrating lymphocytes (TILs) could be targeted to improve tumor control, we administered anti-LAG-3 and anti-PD-1 ICB after two doses of chemotherapy and found combination therapy generated robust antitumor responses compared with each agent alone." (PMID 39343508, 2024). "Interestingly, BTLA, CD200, IDO1, LAG3, TNFSF14, etc., were overexpressed in the low-risk group, suggesting that low-risk patients may get better treatment outcomes in tumor immunotherapy." (PMID 38169540, 2024). "Thus, LAG3 upregulation in HCC may be due to its role in tumor-mediated immune escape and immune regulation." (PMID 39944754, 2024). "Interestingly, in colorectal cancer (CRC), CYT has been shown associate with different mutational events and -CYThigh tumors are related to an increased tumor mutational burden (TMB) and upregulate the expression levels of immune checkpoints, including PD-1, PD-L1/2, CTLA-4, LAG3, and IDO1." (PMID 38612436, 2024). "In addition, the study demonstrated that bispecific antibodies targeting LAG-3 and PD-L1 elicit an effective anti-tumor response from immune cells in the tumor microenvironment, although these results further support the potential of targeting LAG-3 as a cancer immunotherapy." (PMID 39845973, 2024). "Similarly, LAG-3 blockade delayed tumor development in HNSCC, NSCLC, and fibrosarcoma models." (PMID 39425148, 2024). "This upregulation of LAG3 may limit effective anti-tumor immune response." (PMID 39944754, 2024). "Thus, inhibiting the PD-1 and LAG-3 signaling pathways may help reverse T-cell immunosuppression, thereby enhancing the anti-tumor immune response." (PMID 38627681, 2024).
tumor (continued). "We found a negative correlation between TIGIT positivity on T cells and PD-1 and LAG3 protein levels on tumor-infiltrating immune cells, supporting the hypothesis that TIGIT upregulation may compensate for low expression levels of other immune checkpoint proteins in RCC." (PMID 39105820, 2024). "Similarly, LAG-3 is expressed on the surface of activated T cells and is emerging as an important IC in supressing several arms of the anti-tumour repertoire of immune cells and is garnering a lot of attention as a therapeutic target to reinvigorate exhausted T cells." (PMID 36445478, 2023). "We chose to target PD-L1 over PD-1 because by binding PD-L1 on cancer cells or APCs and TIGIT/LAG-3 on T cells, these antibodies can bridge APCs and cancer cells with T cells, improving the quality of immune synapses, and resulting in stronger T cell activation and tumor cell killing." (PMID 37332070, 2023). "In PD-L1/LAG-3 double knock-in mice bearing human PD-L1 knock-in MC3 tumors, IBI323 exhibited stronger antitumor activity than each parental antibody, and these antitumor responses were associated with an increase in the number of tumor-specific CD8+ and CD4+ T cells." (PMID 37670328, 2023). "One hypothesis could be that the low level of LAG3 expression may lead to an exhausted phenotype, but up-regulation of LAG3 may initiate negative feedback of inhibitory signals that creates an active immune environment in the tumor and improve prognosis." (PMID 36765348, 2023). "Furthermore, a recent retrospective study showed that treatment with Nivolumab plus Relatlimab could have a reduced efficacy in patients with type 2 diabetes, possibly due to a low expression of LAG-3 in tumor tissue." (PMID 38201531, 2023). "Blocking both PD-1 and LAG-3 may result in tumor retrogradation." (PMID 38328405, 2023). "Furthermore, LAG-3 has been identified as an indicator of tumor prognosis." (PMID 37237550, 2023). "Additionally, analysis of the tumor-infiltrating T cell tSNE maps revealed a much more localized and focal pattern of expression for LAG-3 (particularly surface LAG-3) compared to the other co-inhibitory and co-stimulatory receptors, which were more broadly expressed." (PMID 37795090, 2023). "We have developed multispecific antibodies targeting PD-L1, TIGIT, and LAG-3 and evaluated them with carefully designed in vitro and in vivo assays, which show that these antibodies efficiently promote T cell activation and cancer cell killing and suppress tumor growth." (PMID 37332070, 2023). "Alternative inhibitory receptors have been identified that may be targeted for anti-tumor immune therapy, such as lymphocyte-activation gene-3 (LAG-3), as have several potential target oncogenes for molecularly targeted therapy, such as tyrosine kinase inhibitors." (PMID 37507765, 2023). "In this study, we show that LAG-3 is a feasible target for generating a predictive imaging biomarker, with [89Zr]Zr-BI 754111 demonstrating a favorable tumor-to-background uptake, target specificity, and correlation with the immune status of the tumor biopsies at baseline." (PMID 36859619, 2023). "Controversial to survival analysis, these observations suggested that the LAG3 expression on lymphocytes infiltrated into tumor tissue may trigger suppressive immune responses and facilitates tumor cell proliferation, resulting in disease progression and tumor recurrence or metastasis." (PMID 36765348, 2023). "Additionally, novel approaches to safely target 4-1BB co-stimulation to the tumor and circumvent previously observed severe liver toxicity may represent an attractive IO combination strategy to further augment PD-1 and LAG-3 dual blockade." (PMID 37795090, 2023). "Moreover, adaptive upregulation of LAG-3 expression may result in treatment resistance and tumor progression in patients receiving anti-PD-1 therapy, and anti-LAG-3 in combination with nivolumab could potentially restore T cell activation and tumor response." (PMID 37004702, 2023).
tumor (continued). "The unique marker phenotype of the tumor-infiltrating PD-1+ LAG-3+ CD8 memory T cell subsets characterized here indicates that this subset of cells may similarly possess tumor-reactive yet dysfunctional features and may be amenable to reinvigoration by combination PD-1 and LAG-3 blockade." (PMID 37795090, 2023). "Based on these results, PD-1 and LAG-3 may function in synergy in a tumor microenvironment." (PMID 36674905, 2023). "Therefore, our results suggest that LAG3 expression regulates the tumor immune system and could affect ICIs therapy." (PMID 38062416, 2023). "Therefore, the synchronous inhibition of LAG-3 and PD-1 may be a new strategy for alleviating tumor immunotherapy resistance." (PMID 37305389, 2023). "Also, critical immune checkpoint genes such as LAG3, PDCD1LG2, CD274, IDO1, PDCD1, and CTLA4 were evaluated because these genes are activated when T cells identify and attach to associated proteins on other cells, such as certain tumor cells." (PMID 37876438, 2023). "Furthermore, we discovered that L1CAM was linked to immune cell infiltration and ICG (CD274, LAG3, PDCD1LG2, CTLA4), and we hypothesized that L1CAM may have a regulatory role in the tumor microenvironment, influencing tumor growth and metastasis." (PMID 36212450, 2022). "Another key finding of the present study was that the number of either TIM-3+ CD8+ T cells or LAG-3+ CD8+ T cells in the spleen was significantly decreased by the activation of D1-receptor-expressing neurons in the medial shell of the nucleus accumbens of tumor-bearing mice." (PMID 35172858, 2022). "In addition, PD-1 and LAG-3 blockade improve anti-tumor vaccine efficacy." (PMID 35874717, 2022). "Thus, anti-LAG-3 and anti-PD-1 antibodies showed synergistic anti-tumor activity in CRC model mice." (PMID 35911673, 2022). "Besides the inherent limitations of the TIDE analysis, one possible explanation would likely be that the T cell dysfunction with multiple alternative immune checkpoints including CTLA-4 and LAG3 within the tumor microenvironment is beyond the salvage of the single-target immune checkpoint inhibitor." (PMID 36092894, 2022). "Effectively, MSI-H tumors express higher levels of tumor-infiltrating lymphocytes (TILs), cytotoxic T-lymphocyte-associated protein 4 (CTLA4), programmed cell death 1 (PD1)/PD-ligand 1 (PD-L1), indoleamine 2,3-dioxygenase (IDO), and lymphocyte-activation gene 3 (LAG-3)." (PMID 36294987, 2022). "Therefore, we aimed to identify whether LAG3 blockade could significantly enhance the MWA-induced anti-tumor immune response by introducing more inflamed tumors and more functional CD8+ T cells." (PMID 36180876, 2022). "Hence, synchronous LAG-3 and PD-1 inhibition may be a potential new strategy for tumour immunotherapy." (PMID 35494015, 2022). "Increased hepatic tumor load and intrinsic tumor factors such as low tumor mutational burden, PD1/PDL1 expression levels, and increased presence of alternative immunosuppressive molecules like Lymphocyte-activation gene-3 (LAG3) in mUM compared to mCM may explain such inefficacy." (PMID 36761417, 2022). "Therefore, blocking PD-1 and LAG-3 signal pathways simultaneously may bring a better anti-tumor effect." (PMID 36518768, 2022). "It is now generally believed that the mechanism of tumor immune escape is the persistent chronic immune stimulation caused by tumor antigens, exhausting T cells and losing most of their effector properties, and the exhausted T cells upregulate PD-1, CTLA-4, LAG-3, and other immune checkpoints." (PMID 36612165, 2022). "T-cell immunoglobulin and mucin domain-containing protein-3 (TIM-3), lymphocyte activation gene-3 (LAG-3), and T-cell immunoglobulin and ITIM domain (TIGIT) were recently identified as immune checkpoint proteins that regulate immune function and have been associated with tumor development." (PMID 35559250, 2022).
tumor (continued). "LAG3 may serve as a biomarker for a strong immune response, and the two opposite immune functions (positively or negatively) of LAG3 can be attributed to the complexity of tumor immune microenvironment and tumor heterogeneity." (PMID 35530341, 2022). "Moreover, preclinical studies demonstrate that IBI323, a bispecific antibody against PD-L1/LAG-3, improves tumor-specific immunity, suggesting that dual-blockade bispecific antibodies targeting PD-L1 and LAG-3 may represent a viable treatment option." (PMID 36119533, 2022). "LAG-3 negatively regulates the function of T cells and plays significant roles in maintaining the homeostasis of immune system under normal physiological conditions and promoting tumor cells immune escape in the tumor microenvironment, indicating a promising target for tumor immunotherapy." (PMID 35958563, 2022). "LAG3 could be detected on tumor-infiltrating lymphocytes, B cells, natural killer cells, and Tregs." (PMID 35296002, 2022). "In addition, we noticed that the expression of LAG3 and GZMK is higher than that of immune inhibitors, such as PD-L1, TIM3, and CTLA4, in the CD8+ T_3 cluster; thus, LAG3 or GZMK may be a better target for tumor immunotherapy in ccRCC." (PMID 35812372, 2022). "Various immune checkpoints are the mature targets in tumor immunotherapy, like PD1/PD-L1 (Programmed Cell Death 1/ Programmed Cell Death Ligand 1), CTLA4 (Cytotoxic T-Lymphocyte Associated Protein 4) and LAG3 (Lymphocyte Activating 3), are in ongoing clinical trials." (PMID 35831836, 2022). "Furthermore, Galectin-3 expressed by a variety of cells in the tumor microenvironment instead of the tumor itself may interact with LAG3 on tumor-specific CD8+ T cells, thus resulting in the modulation of anti-tumor immune responses." (PMID 35958563, 2022). "LAG-3 as an inhibitory receptor expressed on activated T cells can downregulate T-cell function and participate in T-cell exhaustion and tumor immune escape thus promoting tumor progression, and this immunoglobulin superfamily gene was also expressed on NK, DCs, and B cells." (PMID 36225938, 2022). "Hence, the pre-existing anticancer activities of patients with high risk scores may be restrained by the higher level of tumour infiltrated macrophages (M2) and the over-expression of many inhibitory immune checkpoints (such as CD274 and LAG3)." (PMID 34975891, 2021). "Therefore, blocking the LAG-3/MHC-II interaction may be an effective strategy to inhibit tumor immune escape." (PMID 34943817, 2021). "This analysis confirmed the NanoString expression data and showed that tumor-infiltrating human lymphocytes expressed high levels of PD-1, T-cell immunoglobulin and mucin-domain containing-3 (TIM-3), cytotoxic T-lymphocyte-associated protein-4 (CTLA-4) and lymphocyte-activation gene-3 (LAG-3)." (PMID 33589524, 2021). "Unfortunately, tumor-infiltrating CD8+ T cells are frequently in a state of exhaustion, characterized by a progressive loss of effector functions, robust activation of the T-cell exhaustion driver TOX31–34, and sustained expression of inhibitory receptors such as PD-1, LAG-3, Tim-3, and CTLA-428,29." (PMID 34108491, 2021). "Furthermore, the hypomethylation of LAG3 promoter and the hypermethylation of the CTCF binding cite may increase the infiltration of immune cells, indicating that the methylation of LAG3 may become a new epigenetic marker for tumor immune cell infiltration." (PMID 35111155, 2021). "At the same time, its expression level was positively correlated with tumor development, suggesting that interruption of LAG-3 may enhance anti-tumor immunity.LAG-3 not only inhibits T cell activation and proliferation, but also promotes the activity of regulatory cells (Tregs)." (PMID 34869005, 2021). "Thus, we formulated the hypothesis that elevated numbers of VISTA-, LAG3-, IDO-, and TIM3-positive lymphocytes in the tumor microenvironment of PDAC are associated with poor prognosis." (PMID 34072549, 2021).
tumor (continued). "The combination of antibodies (Abs) blocking PD-1 and LAG-3 is also of great interest due to their expression on tumor infiltrating lymphocytes (TILs), thereby restricting T-cell responses to the tumor microenvironment (TME), and which might lead to a favorable safety profile." (PMID 33466653, 2021). "The best characterized inhibitory receptors on tumor-infiltrating lymphocytes (TILs) are programmed cell death protein 1 (PD-1), cytotoxic T lymphocyte associated-antigen 4 (CTLA-4), lymphocyte-activation gene 3 (LAG-3) and T cell immunoglobulin and mucin-domain containing 3 (TIM-3)." (PMID 34571883, 2021). "Indeed, the CD8+ TILs that bind galectin-3 in the tumor microenvironment co-express LAG-3 and PD-1." (PMID 34572756, 2021). "Hence, bispecific antibodies (block PD-L1 and LAG3) may be a novel direction in future tumor treatment." (PMID 35111155, 2021). "Some potential predictive biomarkers have been identified up to now, such as tumor mutational burden (TMB), mismatch repair deficiency (dMMR), immune cell infiltration, and inhibitory receptors related gene expression such as PD-1, PD-L1, CTLA-4, LAG-3, TIM3, and TIGIT." (PMID 34367952, 2021). "This is because JAK1 mutations modulate the tumour immune microenvironment through the depletion of TILs, which results in IFN-γ insensitivity through epigenetic silencing of interferon-signalling components, or increased expression of negative regulators such as PD-1, TIM-3, CTLA-4, and LAG-3." (PMID 34968365, 2021). "Also, XmAb®22841 (a bispecific antibody that simultaneously targets immune checkpoint receptors CTLA-4 and LAG-3 to promote tumor-selective T-cell activation) has been evaluated in the DUET-4 trial in combination with pembrolizumab (ClinicalTrials.gov Identifier: NCT03849469)." (PMID 34063238, 2021). "Also, fewer LAG3+TIM3+PD-1+ T cells were detected in the tumor tissue of the CTLA4-T group." (PMID 33868277, 2021). "Treatment failure might be finally attributable to insufficient T-cell responses (transient, low avidity, low magnitude); poor T-cell homing to Mlh1−/− tumors, dysfunction or death of T cells within the tumor, and immune escape mediated by upregulation of immune-checkpoint molecules LAG-3 and PD-L1." (PMID 33087163, 2020). "Dual blockade of LAG3 and PD-1 might enhance anti-tumor immunity in a synergistic manner." (PMID 33488573, 2020). "In addition, we found that another transcription factor, RBPJ, was overexpressed in tumor-infiltrate Tregs and might regulate the LAG3." (PMID 32039830, 2020). "Therefore, the LAG-3 blockade increases immunity against tumor cells." (PMID 33167514, 2020). "Moreover, together with the co-expression of PD-1, the anti-tumor immunity of CD8+ T cells could be abolished through the interaction with LAG-3’s other ligands i.e., LSECtin, FGL-1, and Gal-3 found in the TME." (PMID 33374804, 2020). "Persistent antigen exposure in the tumor microenvironment possibly results in maintenance of LAG-3 expression on inflammatory cells, which contributes to a state of exhaustion (e.g., impaired proliferation of T-cells and cytokine production) and can enhance anti-tumor T-cell response." (PMID 33396515, 2020). "Both anti-FGL1 and anti-LAG3 could promote anti-tumor T cell immunity." (PMID 33344447, 2020). "Additionally, it demonstrates how LAG3 might function as an important component in anti-tumor immunotherapy." (PMID 33488573, 2020). "In another study, it was demonstrated that most of the intra-tumor CD4+Foxp3+ Treg cells have a Helios+, CTLA-4+, and CD39+ phenotype, but 30% of CD4+Foxp3− cells also expressed markers associated with regulatory functions, including CD25, LAG-3, and latency-associated peptide (LAP)." (PMID 32674255, 2020).